ERBB2 (erb-b2 receptor tyrosine kinase 2)
Diseases named in the same sentence as ERBB2 in open-access papers (continued):
Sharing a sentence is not in itself a finding about the gene and the disease.
breast cancer (continued). "For example, miR-125a, miR-125b, and miR-205 have been reported to functionally cooperate to downregulate the erbB receptor tyrosine kinase family components erbB2/erbB3 in breast cancer cells." (PMID 29312571, 2017). "To characterize early events occurring at the level of the PM upon Tz binding to ERBB2, we analyzed the breast cancer cell line SK-BR-3, in a time range between 2 and 120 min of treatment with Tz." (PMID 28947957, 2017). "Lapatinib is primarily used in patients with advanced-stage, ERBB2-positive breast cancer that has stopped responding to anthracyclines, taxanes, and herceptin." (PMID 28415602, 2017). "The phosphatidylinositol 3-kinase (PI3K) pathway is frequently activated in breast cancers due to (i) amplification of ERBB2, an oncogene that stimulates the PI3K pathway and (ii) activating mutations of the PI3K catalytic subunit, PIK3CA." (PMID 28561737, 2017). "We also obtained the similar results using other ErbB2‐overexpressing breast cancer cell lines, MDA‐MB‐453 and SKBR3 in both of which miR‐205 expression was reduced compared with MCF10A." (PMID 28781955, 2017). "S310F (two cases) and V842I substitutions (two cases) in ERBB2 were recurrently detected in this study and have been functionally characterized as activating and sensitive to lapatinib in ERBB2-negative breast cancers." (PMID 29050249, 2017). "As these pathways are critical for the survival of ErbB2-overexpressing breast cancer cells, our results not only explain the general inhibitory actions of phenformin, but also underscore the value of phenformin in ErbB2+ breast cancer treatments." (PMID 28947975, 2017). "For example, lapatinib was reported to markedly inhibit the expression of survivin, an inhibitor of apoptosis protein (IAP), and enhance apoptosis in ErbB2-overexpressing breast cancer cells." (PMID 28938602, 2017). "ErbB2 antibodies are being used clinically to detect breast cancer metastases in vivo with whole-body imaging methods, such as PET and SPECT13,14." (PMID 29089571, 2017). "Here, we found that miR–1296-5p inhibits the proliferation of ERBB2-positive breast cancer cells by decreasing ERBB2 expression." (PMID 29089858, 2017). "Relative ratio of ERBB2/ERBB1 heterodimers on the plasma membrane varies among breast cancer cell lines; in the widely used SK-BR-3 line it was found to be approximately 3.2." (PMID 28947957, 2017). "The MBS algorithm was applied to the TCGA expression profile data with breast cancer molecular subtype data; luminal A, luminal B, triple negative/basal-like, and ERBB2/HER2+." (PMID 28793339, 2017). "Consistent results were obtained in the MDA-MB-453 breast cancer cell line, which was also lapatinib resistant and ERBB2 positive and expressed a lower level of ERRF." (PMID 28415602, 2017). "In a phase II randomized study where drug activity and safety were evaluated in ERBB2 positive operable breast cancer, patients were treated with chemotherapy as a neoadjuvant therapy and lapatinib as a targeted therapy." (PMID 28415602, 2017). "Current conventional therapy to target ERBB2 antigen in breast cancer includes treatment with trastuzumab, a humanized monoclonal antibody that binds to the extracellular domain of the receptor." (PMID 28885562, 2017). "On the other hand, ErbB2 degradation by autophagy in breast cancer cells was recently reported requiring polyubiquitinationin." (PMID 28338617, 2017). "Commonly used clinically for breast cancer therapy, this antibody has recently been repurposed to visualize ErbB2 expression using PET and SPECT13,14." (PMID 29089571, 2017). "MIEN1 is located in the chromosomal region 17q12-21 and is typically amplified along with its neighboring gene ERBB2 in breast cancer." (PMID 28476046, 2017). "In particular, ZNF217, which is located on 20q13 near the locus that encodes RAE1, was previously reported as a novel breast cancer gene along with EGFR1, ERBB2, and PPMID26." (PMID 28181567, 2017).
breast cancer (continued). "Unfortunately, breast cancer cells have developed drug resistance through shedding ErbB2 away from the targeting by trastuzumab, the truncation of ErbB2, or alterations in the downstream signaling pathways." (PMID 28338617, 2017). "Our study suggests that short-term, low dose lapatinib exposure during the premalignant phase of breast cancer development is a promising strategy to prevent the development of erbB-2-overexpressing mammary tumors." (PMID 28061785, 2017). "ERRF expression decreased while its knockdown increased ERBB2 expression in breast cancer cells as well, it is also possible that ERRF loss upregulates ERBB2 including mtERBB2 to decrease lapatinib sensitivity." (PMID 28415602, 2017). "In an effort to understand them we found that in order to produce ErbB2, detached breast cancer cells require the activity of an ErbB2 effector protein kinase Mek and that Mek-driven ErbB2 expression is neccesary for anchorage-independent growth of such cells." (PMID 29285258, 2017). "In summary, we have identified a novel mechanism of the regulation of ErbB2 expression in breast cancer cells." (PMID 29285258, 2017). "Several previous studies have suggested that, in breast cancer cells overexpressing ErbB2/HER2, it localizes to membrane ruffles or protrusions together with its signaling partners, ErbB1/EGFR and ErbB3/HER3." (PMID 28369073, 2017). "Using ErbB2-overexpressing breast cancer cell and animal models, including MMTV-ErbB2 mice, our current study reveals anti-proliferative effects of AZD4547 treatment in vitro and in vivo." (PMID 28900173, 2017). "One of the targeted therapies is the Lapatinib, a dual tyrosine kinase inhibitor that interrupts the ERBB2 and EGFR pathway in the treatment of ERBB2 positive breast cancer, which is used as ditosylate and orally active." (PMID 28415602, 2017). "AZD4547 also produced significant cancer preventative and therapeutic effects in our cell and animal models of ErbB2-overexpressing breast cancer." (PMID 28900173, 2017). "For example, trastuzumab, a monoclonal antibody Erbb2 inhibitor used to treat Erbb2+ breast cancer, has been shown to lead to congestive heart failure in 1.7–4.1% of patients and a 10% decrease in LVEF when used alone as treatment." (PMID 28924210, 2017). "In GEAR, ERBB2 has been annotated to enhance cell proliferation and prompt resistance of breast cancer to Letrozole, a drug is used for the treatment of hormonally-responsive breast cancer after surgery." (PMID 28294141, 2017). "For example, it was established that a therapeutic HSP90 antagonist can trigger lysosomal ErbB2 degradation in breast cancer cells." (PMID 29285258, 2017). "In both 2-D and 3-D cell culture models, expression of ERRF sensitizes intrinsically resistant ERBB2 positive breast cancer cells to lapatinib; and in vivo tumorigenesis assay confirmed the effect." (PMID 28415602, 2017). "IHC staining confirmed that lung metastases derived from LPP-shRNA expressing mammary tumours maintained ErbB2 levels, while exhibiting diminished LPP expression." (PMID 28436416, 2017). "During our investigation of the in vitro anti-cancer mechanisms of AZD4547, we found that AZD4547 suppresses cell proliferation and cell cycle progression in ErbB2-overexpressing breast cancer cell lines." (PMID 28900173, 2017). "Selective inhibition of erbB-2/EGFR-mediated signaling presents lapatinib as a promising drug to target erbB-2/EGFR-overexpressing breast cancers." (PMID 28061785, 2017). "Overexpressed miR-1296-5p reduced its target protein level and mTORC1/S6 activation, inhibited the proliferation of ERBB2-positive breast cancer cells and sensitized these cells to cisplatin and 5-fluorouracil-induced apoptosis." (PMID 29089858, 2017). "In patients with ERBB2-positive breast cancer, higher level of ERRF expression correlated with both pathologic complete response (pCR) to lapatinib and better survival." (PMID 28415602, 2017).
breast cancer (continued). "Most breast cancers arise from luminal epithelial cells, and 25–30% of these tumors overexpress the ErbB2/HER2 receptor that correlates with disease progression and poor prognosis." (PMID 28174229, 2017). "The key to developing CSC/TIC inhibitors is to understand the underlying mechanisms that result in selective inhibition of CSC/TIC populations, as demonstrated by buformin in our models of erbB-2-overexpressing breast cancer." (PMID 28193239, 2017). "In contrast, ErbB2-induced mammary tumors exhibited a higher invasive and metastatic potential in AKT1 knock-out mice." (PMID 28765579, 2017). "We found that phenformin significantly inhibits proliferation, migration, invasion, and EMT in ErbB2-overexpressing breast cancer cells and blocks tumor growth in a syngeneic mammary tumor model, which were associated with the inhibition of IGF1R stimulation." (PMID 28947975, 2017). "In ErbB2-positive breast cancer, reduced β-catenin levels lead to the activation of an EMT program characterized by down-regulation of adherens junctions and sustained nuclear localization of β-catenin." (PMID 28798698, 2017). "Trastuzumab is a humanized antibody directed against ERBB2 that revolutionized the treatment of ERBB2 breast cancers." (PMID 28947957, 2017). "Breast cancer (BC) is a heterogeneous disease with multiple subtypes related to the oestrogen receptor (ER) status, the presence of ERBB2 amplification and also the genetic and transcriptomic landscape." (PMID 28451966, 2017). "We showed that alcohol exposure (100 mg/dL) for 10 days caused an increase in the CSC population in cultured MCF-7 breast cancer cells and MCF-7 cells overexpressing ErbB2 (MCF-7-ErbB2 cells)." (PMID 29156633, 2017). "As such, our aim to investigate the efficacy of buformin in various models of erbB-2-overexpressing breast cancer, which accounts for approximately 30% of human breast cancer cases, has provided further evidence of the anti-cancer potential of buformin." (PMID 28193239, 2017). "This is true for colon cancer cells where a cell-specific protein networks modulate Wnt signaling, and for breast cancer where alterations of β-catenin levels drive the progression of the basal category of ErbB2-positive breast cancer." (PMID 28798698, 2017). "The present study is the first, to our knowledge, to demonstrate that LPP is dispensable for primary mammary tumour growth but promotes metastasis of ErbB2-expressing breast cancer cells." (PMID 28436416, 2017). "The results from both SK-BR-3 and BT-474 cell lines indicate that ERRF downregulation causes a level of significantly reduced sensitivity to lapatinib treatment in ERBB2 positive breast cancer cells." (PMID 28415602, 2017). "Once Mek activity is blocked in breast cancer cells, the cells lose ErbB2 and those cells that survive become trastuzumab-resistant." (PMID 29285258, 2017). "To further test the effect of ERRF on lapatinib sensitivity, we used two breast cancer cell lines that were ERBB2 positive and lapatinib sensitive and expressed higher levels of ERRF, i.e., SK-BR-3 and BT-474." (PMID 28415602, 2017). "Therapy of colon and breast cancer with anti-EGFR and anti-ERBB2 antibodies, respectively, and of EGFR mutated lung adenocarcinoma with tyrosine kinase inhibitors is well established." (PMID 27844328, 2017). "In this study, we show that Tz treatment of the ERBB2-overexpressing breast cancer cells, promotes ERBB2/ERBB1 heterodimers and CDR formation." (PMID 28947957, 2017). "Well-understood examples include overexpression of ERBB2 in HER2+ breast cancer and the constitutively active oncogenic fusion protein BCR-ABL, which can cause CML." (PMID 28951721, 2017). "For example, ERBB2 itself is not a known DCM gene in the Mendelian sense, but it is the target of the monoclonal antibody and breast cancer drug, trastuzumab (Herceptin), the current standard of care for HER2+ breast cancer patients." (PMID 29367538, 2017).
breast cancer (continued). "We found that in some cases they are used in current cancer type-specific drugs and drug-therapies; for example, anti-cancer drugs targeting the ERBB2 gene are in use for breast cancer." (PMID 28871116, 2017). "For example, Erb-b2 receptor tyrosine kinase 2 gene (ERBB2, synonym: HER2) was upregulated in one breast cancer sample containing the ATF7-SPATS2 fusion." (PMID 29299133, 2017). "For this purpose, we considered breast cancers, where amplifications of ERBB2 (Chromosome 17), CCND1 (Chromosome 11) and MYC (Chromosome 8) oncogenes are frequently observed (∼15%, 11% and 38%, respectively in the TCGA cohort)." (PMID 29069713, 2017). "Another study of dual-targeted CAR T cells specific for MUC1 and ErbB2 demonstrated their effectiveness against solid tumors, particularly breast cancer." (PMID 29312333, 2017). "In this regard, Herceptin (anti-erbB-2 Ab) has been clinically available for use in improving therapeutic goals in patients with breast cancers that overexpress erbB-2 proteins." (PMID 28460461, 2017). "Tyrosine kinase signaling pathways have been successfully targeted in malignancies, examples include EGFR in non-small cell lung cancer (NSCLC), KIT in gastrointestinal stromal tumors, and ERBB2 breast cancers, to name a few." (PMID 28030802, 2017). "Our findings suggest that miR-1296-5p is involved in the regulation of proliferation in breast cancer cells via targeting ERBB2/mTORC1 signaling pathway." (PMID 29089858, 2017). "While ERBB3 can potentially dimerize with all members of the ERBB family, several lines of evidence show that the strongest dimer to activate survival pathways like AKT in breast cancer is the ERBB3/ERBB2 dimer." (PMID 28060735, 2017). "Previous studies have demonstrated that administration of EGFR/erbB-2-targeting lapatinib to MMTV-erbB-2 transgenic mice inhibited mammary tumor development." (PMID 28061785, 2017). "The clinical evidence that p140Cap correlates with a favourable outcome in ERBB2 breast cancer patients suggest that p140Cap is able to curb the intrinsic biological aggressiveness of ERBB2 tumour." (PMID 28300085, 2017). "ErbB2 is expressed in up to 30% of all breast cancers and in up to 60% of non-invasive breast cancers." (PMID 29089571, 2017). "EGFR protein expression and phosphorylation were also downregulated by AZD4547, suggesting a connection between the EGFR and FGFR families of RTKs in ErbB2-overexpressing breast cancers." (PMID 28900173, 2017). "Our data are consistent with a scenario that Mek promotes ErbB2 expression in breast cancer cells by blocking lysosomal ErbB2 degradation." (PMID 29285258, 2017). "Our lab recently studied the cancer preventative effects of metformin treatment in cell and animal models of erbB-2-overexpressing breast cancer." (PMID 28193239, 2017). "Lapatinib induces growth inhibition and apoptosis in ErbB2-overexpressing breast cancer cells by breaking the CIP2A-Akt feedback loop." (PMID 28938602, 2017). "The introduction of the anti-ErbB2 antibody Trastuzumab (specific for domain IV), in combination with standard chemotherapy, significantly improved the clinical outcome of breast cancer patients." (PMID 28186982, 2017). "Although ERBB2 has not been annotated to this process by GO, ERBB2 positive breast cancers have been shown to produce significantly high amounts of fats and the fat synthetic process is required for survival of ERBB2-positive breast cancer cells." (PMID 27836980, 2017). "In the context of previous reports, our data provide fundamental support of phenformin as a candidate for ErbB2+ breast cancer therapy." (PMID 28947975, 2017). "One of the most impactful therapies for breast cancer is the humanized monoclonal antibody, trastuzumab (Herceptin®), which specifically recognizes the HER2 protein encoded by the ERBB2 gene." (PMID 28101782, 2017). "Collectively, our data are consistent with a scenario that Mek activity prevents lysosomal ErbB2 degradation in detached breast cancer cells." (PMID 29285258, 2017).
breast cancer (continued). "Consistently, alcohol exposure increased the CSC population and induced ErbB2 phosphorylation in the mammary tumors of MMTV-neu mice." (PMID 29156633, 2017). "The targeted ERBB2 therapy, trastuzumab, has had a tremendous impact on management of patients with HER2+ breast cancer, leading to development and increased use of further HER2 targeted therapies." (PMID 28101782, 2017). "It was shown that inhibition of the PP2A catalytic subunit induced apoptosis through p38 MAPK, Caspase 3, and PARP activation in ErbB2-overexpressing breast cancer cells." (PMID 28938602, 2017). "We extended our analyses to other ErbB2-expressing breast cancer cells and a basal breast cancer cell line (BT549)." (PMID 28436416, 2017). "At the surface of the cancer cells, ErbB proteins are regularly overexpressed: at about two millions of EGFR in A-431 human epidermoid carcinoma cells and 105-106 ErbB2 proteins in SK-BR-3 breast cancer cell line." (PMID 28286519, 2017). "Amplification of a locus hosting a proto-oncogene is a common oncogenic mechanism: the ERBB2 locus is amplified in breast cancer and EGFR in glioma multiforme." (PMID 28333948, 2017). "In this study, ERRF was identified in the list of 50 genes whose expression states predicted pCR in 93% of the test tumor samples, suggesting that patients with ERBB2 positive breast cancer, higher ERRF expression predicts a benefit from lapatinib treatment." (PMID 28415602, 2017). "We and others found that ErbB2 blocks anoikis of breast cancer cells by downregulating pro-apoptotic proteins Perp and Bim in a Mek-dependent manner." (PMID 29285258, 2017). "In this study, we investigated the anti-cancer benefits of AZD4547, an FGFR1-3 inhibitor, in ErbB2-overexpressing breast cancer models." (PMID 28900173, 2017). "In mammary tumour cells expressing functionally active ErbB2, the overexpression of mutant ShcA (ShcA/3F), which lacks the three tyrosine residues (Y239/240 and Y317), strikingly affected the ability of ErbB2-transformed cells to secrete VEGF." (PMID 30210578, 2017). "Several well-defined copy number alterations have been identified in cancer, such as ERBB2 in breast cancer, N-MYC in neuroblastoma and EGFR-1 in head and neck tumours and gliomas, which have prognostic as well as predictive implications." (PMID 28697743, 2017). "AZD4547 also inhibited MaSC and TIC populations alongside impaired self-renewal in ErbB2-overexpressing breast cancer cell lines, premalignant mammary tissues from MMTV-ErbB2 mice, and spontaneous tumors." (PMID 28900173, 2017). "We advanced these studies by particular investigation of phenformin-mediated responses in ErbB2-overexpressing breast cancer cells with additional mechanistic insight." (PMID 28947975, 2017). "In search of a molecular mechanism, we decided to exploit SKBR3 breast cancer cells as a model of ERBB2 gene amplification relevant to human breast cancer." (PMID 28300085, 2017). "ERBB2 genes are up-regulated in breast cancers with highly suspicious calcifications (fold change 2.474, p < 0.001)." (PMID 28900139, 2017). "Lapatinib, a small molecule ErbB2/EGFR inhibitor, is FDA-approved for the treatment of metastatic ErbB2-overexpressing breast cancer; however, lapatinib resistance is an emerging clinical challenge." (PMID 28938602, 2017). "Mammary tumor-derived cells that overexpress erbB2 were co-cultured with normal mammary epithelial cells in our in vitro model of cancer cell redirection." (PMID 28594912, 2017). "Metastatic ErbB2-positive breast cancer correlates with increased aggressiveness, poor prognosis, and short overall survival time." (PMID 28417948, 2017). "We have identified in this study a novel mechanism by which a protein kinase Mek controls three-dimensional growth of ErbB2-positive breast cancer cells." (PMID 29285258, 2017).